H2BW2 (H2B.W histone 2)
Description:
Core component of nucleosome. Nucleosomes wrap and compact DNA into chromatin, limiting DNA accessibility to the cellular machineries which require DNA as a template. Histones thereby play a central role in transcription regulation, DNA repair, DNA replication and chromosomal stability. DNA accessibility is regulated via a complex set of post-translational modifications of histones, also called histone code, and nucleosome remodeling.
Synonyms: H2B/s; H2BFM; H2BM
Tractability: No criterion of Open Targets' tractability assessment is met for any kind of drug.
Gene: Protein-coding gene on chromosome X (104,039,956 to 104,042,454, forward strand). Ensembl gene ENSG00000101812.
Subcellular location: Nucleus; Chromosome
Gene Ontology:
Molecular function: DNA binding; structural constituent of chromatin; protein heterodimerization activity
Biological process: chromatin organization
Cellular component: nucleosome; chromosome; nucleus
Homologues: Orthologues: macaque H2BW2A (84% identical), chimpanzee H2BW1 (74% identical), mouse H2bw2 (40% identical). Paralogues in human: H2BW1 (72% identical), H2BC11 (40% identical), H2BC12 (40% identical), H2BC15 (40% identical), H2BC3 (40% identical), H2BC10 (39% identical), H2BC13 (39% identical), H2BC21 (39% identical), H2BC4 (39% identical), H2BC5 (39% identical), H2BC6 (39% identical), H2BC7 (39% identical), and 9 more.
Diseases named in the same sentence as H2BW2 in open-access papers:
H2BW2 is named in the same sentence as 1 disease in open-access papers, as found by Europe PMC text mining. Sharing a sentence is not in itself a finding about the gene and the disease.
H2BW2 shares sentences with these, for which no sentence is quoted: cervical cancer (1 paper).